EGFR (epidermal growth factor receptor)
Diseases named in the same sentence as EGFR in open-access papers (continued):
Sharing a sentence is not in itself a finding about the gene and the disease.
cancer (continued). "Previously known targets for miR-7 include messages for signaling proteins, Pak1 and epidermal growth factor receptor (EGFR), known to be activated in many forms of cancer." (PMID 21454924, 2011). "In this paper, taking the antibody Nimotuzumab as a case study, we would like to share our views regarding clinical implementations of EGFR-targeted therapies that aim to a long-term control of the advanced cancer disease." (PMID 24212794, 2011). "Proteins of MAPK family are a downstream target of EGFR, and have been shown to play a crucial role in cancer cell invasion." (PMID 22188922, 2011). "The epidermal growth factor receptor (EGFR) is a receptor tyrosine kinase over-expressed on many human cancer cells surface, making it a target for anticancer drug delivery." (PMID 21686186, 2011). "We also assumed that the transient rate of change of phospholipase Cγ (PLCγ ), an important molecule in the EGFR pathway, will result in cancer cell migration, whereas a smooth rate of change of PLCγ will result in cancer cell proliferation." (PMID 22176732, 2011). "Alternatively, drugs can be actively targeted to tumors through cancer-related receptors (such as folate, Epidermal Growth Factor (EGFR), transferrin)." (PMID 24212654, 2011). "HDACialso decreased the expression of SGLT1, an active glucose transporter found tobe stabilized by EGFR, and suppressed the glucose uptake of cancer cells." (PMID 21464950, 2011). "Targeting cell surface molecules using mAbs is an emerging strategy in cancer therapy, and mAbs against cancer-related surface molecules such as EGFR, HER2 and CD20 have been successfully employed." (PMID 21573021, 2011). "The biological functions of cancer cells are remarkably suppressed when specific blockers inhibit EGFR phosphorylation." (PMID 22087246, 2011). "Although several studies have shown that EGFR translocates into the mitochondria in cancer cells, it remains unclear whether mitochondrially localized EGFR has an impact on the cells and whether EGFRvIII, a constitutively activated variant of EGFR, undergoes mitochondrial transport similar to EGFR." (PMID 21388543, 2011). "This set contains many classical cancer genes that are involved in major signaling pathways (i.e. TGFb, EGFR, MAPK, PI3K/AKT signaling)." (PMID 21575214, 2011). "Targeted therapies shows considerable promise for the future of cancer treatment and much attention has been focused on developing inhibitors of the EGFR-mediated signaling pathway." (PMID 22096483, 2011). "The contribution of the EGFR pathway to oncogenesis has been well documented, and therapeutic exploitation of this axis has proven to be successful for several types of cancers, including colorectal and head and neck cancers." (PMID 21722395, 2011). "Treatment of patients suffering from EGFR-mutant cancers with EGFR inhibitors leads to objective response, to a doubling in progression-free survival as compared to standard chemotherapy and to long overall survival." (PMID 21573178, 2011). "Overexpression of Her2/ErbB2/Neu, a member of the epidermal growth factor receptor (EGFR)-family tyrosine kinases, in malignant tumors is often correlated with recurrent distant metastasis." (PMID 21966491, 2011). "For example, EGFR is a well-studied cancer gene that is differentially expressed in a number of cancers and is used in clinical settings as a therapeutic target." (PMID 21326606, 2011). "In recent years, several EGFR inhibitors have been developed to treat advanced cancers by disrupting PI3K/Akt signaling cascades and circumventing the development of metastasis." (PMID 21966417, 2011). "The identification of many well-defined cancer gene markers (representing oncogenes), such as EGFR, osteopontin (SPP1), ERBB3, MALAT1, S100A2, S100A6, ABCC3 and ELN3, as highly discriminative genes by the ECD is quite encouraging." (PMID 22369099, 2011). "We have just simulated the normal state of EGFR addicted cancer cells, namely a setting of sustained EGFR activation." (PMID 22194952, 2011).
cancer (continued). "Targeted therapies against EGFR in cancer treatment have been disappointing due to the robust nature of EGFR signalling." (PMID 21738726, 2011). "Clinical benefit from EGFR-targeted therapies is well documented; however, chronic use in advanced cancer patients has been limited due to cumulative and chemotherapy-enhanced toxicity." (PMID 24212794, 2011). "The epithelial growth factor receptor (EGFR; also known as Her or ErbB) family of receptor tyrosine kinases has been shown to have oncogenic roles in a number of human cancers." (PMID 21364581, 2011). "Although well studied, many questions still remain unanswered about the interaction of EGF with EGFR, the resulting signaling and its involvement in cancer." (PMID 21931838, 2011). "Although not as sensitive as patients harboring these mutations, some patients with wild-type EGFR (wtEGFR) remain responsive to EGFR TKIs, suggesting that the existence of unexplored mechanisms renders most of wtEGFR-expressing cancer cells insensitive." (PMID 21731744, 2011). "Emerging evidence indicates that upon activation, some of EGFR or its family members in cancer cells relocate to the nucleus, where they participate in the regulation of gene transcription, cell cycle checkpoints and DNA repair." (PMID 22085699, 2011). "It is therefore postulated that the widespread phenomenon of EGFR over-expression in human cancers occurs, at least in part, as a consequence of common pathological events, other than genomic changes, associated with solid tumors." (PMID 21917153, 2011). "Overall, the analysis presented in this paper allows understanding of the impacts of cancer-related abnormalities on the EGFR signaling pathway." (PMID 21333004, 2011). "A nuclear translocalization mode of EGFR has recently been reported in a variety of cancer cell types, and the effect of cetuximab on nuclear EGFR has been investigated with variable results." (PMID 22091418, 2011). "OSI Pharmaceuticals investigated the properties of cancer cells resistant to EGFR inhibition and found that this subpopulation of cells displayed properties of EMT, including an increased dependence on PDGFR signaling." (PMID 21725138, 2011). "Epidermal growth factor receptor (EGFR) plays an important role in the development and progression of a variety of malignant tumors and mutated EGFR status is a known predictor of response to tyrosine kinase inhibitors (TKIs)." (PMID 24212786, 2011). "Two modes of EGFR signaling, cell-surface and nuclear, have been well characterized to play important roles in human cancers." (PMID 21388543, 2011). "Previous studies have indicated there are cross-talks between the E-cad and EGFR pathways regulating the growth of various types of cancer." (PMID 21939503, 2011). "This ability of EGFR, to function despite treatment with tyrosine kinase inhibitors and targeting antibodies, poses a major problem for cancer therapy." (PMID 21738726, 2011). "The receptor-specific monoclonal antibodies bevacizumab and cetuximab have shown remarkable outcome in vascular growth factor receptor- (VEGF-) positive and epidermal growth factor receptor (EGFR)-positive cancer, respectively." (PMID 20981352, 2011). "Collectively, an upregulation of TACE-mediated sheddase activity would thus lead to elevated EGFR-derived oncogenic drive in cancer cells, as it is widely accepted that triggering the EGFR downstream cascade is crucial for carcinogenesis." (PMID 21102583, 2011). "In contrast, 11C-gefitinib showed enhanced accumulation in vitro in the cancer cells that had the highest EGFR expression." (PMID 22095231, 2011). "The particular activation or inhibition of downstream EGFR signaling appears to influence cancer cell apoptotic responses to versican mediated effects and appear variably modulated dependant on chemotherapeutic drug or EGFR inhibitor delivered." (PMID 22096483, 2011). "Both classes of therapy inhibit the signal transduction of EGFR and are approved for many advanced cancers." (PMID 21966417, 2011).
cancer (continued). "Our study indicated that either EGFR inhibitor at low concentration suppressed the proliferation of cancer cells in combination with SN38." (PMID 21997136, 2011). "The true role of KRAS mutations in regards to EGFR therapy for PDAC is yet to be fully discovered and careful cancer-type distinction must be employed as there is little evidence demonstrating true prognostic power of this clinical marker." (PMID 21792199, 2011). "Phosphorylation of EGFR activates complex down stream signaling events leading to proliferation, migration, invasion, and inhibition of apoptosis of cancer cells." (PMID 21738572, 2011). "The EGFR is infamous for its role in cancer; however, it is also involved in regulation of nitric oxide (NO) production, and has been shown to induce relaxation of various vascular beds." (PMID 21476970, 2011). "In this section, we shall simulate the network response upon acute EGFR inactivation, which mimics the situation of using the EGFR inhibitors in EGFR addicted cancer cells." (PMID 22194952, 2011). "The epidermal growth factor receptor (EGFR) is overexpressed in many different cancers and is currently seen as a promising target for cancer therapy." (PMID 24212824, 2011). "The EGFR-mediated signal transduction pathway was revealed to be inhibited by anti-LeY antibodies, which leads to apoptosis of cancer cells." (PMID 22174601, 2011). "Both EGFR antibodies and EGFR-TKIs are widely used to treat cancer patient by inhibition of EGFR, revealing a new link between EGFR inhibition and autophagy activation." (PMID 21655094, 2011). "EGFR is known to be crucial for cancer cell survival and differentiation and is therefore a target for cancer therapy using EGFR inhibitors." (PMID 21284875, 2011). "EGFR overexpression has been documented extensively in a wide variety of malignant tumors, including squamous cell carcinoma of the head and neck (SCCHN)." (PMID 21939503, 2011). "Substantial evidence implicating ADAM-mediated growth factor ligand release and EGFR signalling in cancer cell proliferation or migration is now available." (PMID 21906355, 2011). "Cancer-associated fibroblasts-derived NRG-1 promote PDAC tumourigenesis via ErbB3-AKT signalling and overcomes single-agent EGFR inhibition." (PMID 21792199, 2011). "Epidermal growth factor receptor (EGFR) is also over-expressed in many types of cancers, including NSCLC and we have shown that this is co-expressed in the epithelium as part of the whole 'COPD phenotype signal'." (PMID 21970519, 2011). "Other studies have demonstrated sequence-dependent interaction between EGFR-TKIs and chemotherapy in human cancer cell lines." (PMID 21255411, 2011). "Wortmannin, an inhibitor of PI3K, and genistein, a phytoestrogen down-regulating tyrosine kinase, have been used in cancer research demonstrating inhibition of cancer motility and EGFR signaling inhibition, respectively." (PMID 21305029, 2011). "Curcumin showed potential effects on inhibiting cancer cell proliferations and can induce EGFR degradation in gefitinib-resistant NSCLC cell lines." (PMID 21858220, 2011). "Molecular therapeutics for treating epidermal growth factor receptor-(EGFR-) expressing cancers are a specific method for treating cancers compared to general cell loss with standard cytotoxic therapeutics." (PMID 21776391, 2011). "While EGF first stimulates the activation of the EGFR and subsequently increases cancer cell proliferation, EGF concurrently induces the activation of ROCK, which then turns off the activated EGFR pathway via a negative feedback system." (PMID 21722395, 2011). "It is thought that either c-Met or EGFR stands at the top of the hierarchy of the downstream signalling pathway governed by the two molecules in a subset of cancer." (PMID 21673683, 2011). "When applied to EGFR-expressing cancer cells the aptamer inhibits EGFR-mediated signal pathways causing selective cell death." (PMID 21915281, 2011).
cancer (continued). "We also conducted a series of experiments to address the impact of the mitochondrial accumulation of EGFR and EGFRvIII on the apoptotic response of cancer cells treated with apoptosis-inducing agents and an EGFR kinase inhibitor, Iressa." (PMID 21388543, 2011). "The low frequency of EGFR mutant cancers precluded statistically meaningful analysis of transcriptional data according to EGFR genotype." (PMID 21385341, 2011). "EGFR and one of its small molecule inhibitor, Gefitinib, is a canonical example of RTKs, cancer and targeted therapeutics." (PMID 21701703, 2011). "Together, these results indicate that apoptotic stimuli enhance EGFR mitochondrial translocalization in human cancer cells." (PMID 21388543, 2011). "We next evaluated the targets inhibition of AST1306 in human cancer cells that overexpress EGFR and/or ErbB2." (PMID 21789172, 2011). "Activation of the epidermal growth factor receptor (EGFR) via PG E2 action is of great interest since EGFR is recognized as a therapeutic target in the cancer setting and several EGFR inhibitors have been developed." (PMID 24250402, 2011). "The monoclonal anti-EGFR antibody, Cetuximab (C225), is a unique targeting agent to target EGFR-positive cancer cells." (PMID 21738572, 2011). "EGFR has been shown to mediate at least two pathways in cancer cells: the cytosolic and the nuclear pathways." (PMID 22085699, 2011). "The antiproliferative effects of AST1306 were then evaluated in a panel of human cancer cell lines with varying levels of EGFR and ErbB2 expression." (PMID 21789172, 2011). "Wnt/β-catenin overexpression was shown to activate signalling via EGFR, while EGFR can form a complex with β-catenin in cancer cells thereby increasing invasion and metastasis." (PMID 22091418, 2011). "Both PGE2 and AR induce epithelial cell proliferation through EGFR activation and uncontrolled activation of this pathway is known to result in the development of cancer." (PMID 24212947, 2011). "The epidermal growth factor receptor (EGFR) is involved in the development and the progression of several human cancers, including NSCLC." (PMID 21750552, 2011). "Accumulated evidence has suggested that cross-talk occurs between c-Met and EGFR in several cancer cell lines." (PMID 21673683, 2011). "We found that, as a consequence of the EGFR inhibition, CL4 strongly inhibits the anti-apoptotic STAT3 and induces cell death selectively in EGFR-positive cancer cells by activation of caspase-3, caspase-8 and PARP." (PMID 21915281, 2011). "Equally important, is the fact that activation of the MapK/ERK pathway via EGFR stimulation is vital for increased transcription of numerous cancer related genes." (PMID 21992608, 2011). "Meanwhile, estrogen transactivate receptor tyrosine kinases (including epidermal growth factor receptor and insulin-like growth factor receptor), resulting in growth factor-like effects that transform cancer cell into an invasive phenotype." (PMID 21818323, 2011). "It has also been suggested that EGFR signaling plays central roles in cancer pathogenesis and progression." (PMID 22087246, 2011). "Consider EGFR as an example to show how inhibition by Nelfinavir can result in an anti-cancer effect." (PMID 21552547, 2011). "Gefitinib (Iressa®, AstraZeneca plc, London, UK) and Erlotinib (Tarceva®, Genentech, Inc., San Francisco, CA) are examples of anti-cancer drugs targeting EGFR-TK." (PMID 21943352, 2011). "In many cases, enhanced EGFR signaling leads to abnormal cellular processes and often induces cancer." (PMID 21333004, 2011). "The current drug delivery system actively targets MDR cancer cells through EGFR binding; the surface of the nanocarriers have been modified with an EGFR-specific peptide." (PMID 21931642, 2011).
cancer (continued). "Activation of the EGFR can trigger intracellular signal transduction and subsequent cancer cell proliferation, inhibition of apoptosis, neoangiogenesis, and further metastasis, all of which are important for the development of the cancer phenotype." (PMID 24212826, 2011). "Epidermal growth factor receptor (EGFR) plays an essential role in normal development, tumorigenesis and malignant biology of human cancers, and is known to undergo intracellular trafficking to subcellular organelles." (PMID 21388543, 2011). "The aim of this study was to provide new information on the intricate interaction pattern of EGF and EGFR by comparing the kinetics and the affinity of the 125I-EGF-EGFR interaction in four cancer cell lines." (PMID 21304974, 2011). "The CN gain of EGFR gene, a well-known cancer gene and drug target, was commonly found in CRC MSS tumors (8 out of 13 samples, 62%) according to genome-wide CNA analysis." (PMID 21645411, 2011). "Our findings demonstrate that both EGFR and EGFRvIII undergo mitochondrial translocalization when cancer cells encounter apoptotic stimuli." (PMID 21388543, 2011). "As one of receptor tyrosine kinases (RTKs) important to cancer cell growth, proliferation, invasion, and metastasis, epidermal growth factor receptor (EGFR) was frequently deregulated in NSCLCs." (PMID 21655094, 2011). "We are currently developing a cancer vaccine based on the extracellular region of the EGFR, adjuvated with a proteoliposome from the outer membrane of Neisseria meningitidis bacteria." (PMID 24212794, 2011). "In particular, the epidermal growth factor receptor (EGFR) family has been targeted to overcome radiation resistant cancer cell types." (PMID 21496273, 2011). "Stat3 activity in these cancer cells has been shown to depend on autocrine activation of EGFR by secreted TGFα." (PMID 21264347, 2011). "Nuclear EGFR functions as a transcription factor and tyrosine kinase, leading to increased proliferation and poor clinical outcomes in cancer." (PMID 21388543, 2011). "EGFR overexpression has been demonstrated in many human carcinomas including the breast, stomach, esophageal squamous carcinoma, and HCC." (PMID 21829460, 2011). "Because of the high prevalence of EGFR overexpression in carcinomas, inhibitors of epidermal growth factor (EGF) signaling are potential therapeutic agents." (PMID 21829460, 2011). "In carcinoma cells with irreversible loss of polarity, the MUC1-C subunit constitutively interacts with EGFR and promotes EGFR signaling." (PMID 22140559, 2011). "In 65% of patients (41 of 63), cancer tissues showed an overexpression of EGFR compared with normal tissues, whereas 79 and 81% (50 of 63 and 51 of 63, respectively) of patients showed an overexpression of cytoplasmic Her-2 and ErbB3, respectively." (PMID 20216540, 2010). "Further to this is the clinical utilization of anti-EGFR monoclonal antibodies including cetuximab in the treatment of H and N cancers." (PMID 21274259, 2010). "Compared to other RTKs, EGFR is more universally expressed and exhibits higher activity, particularly in cancer cells." (PMID 20074357, 2010). "Epidermal growth factor receptor (EGFR) is a type 1 membrane tyrosine kinase that plays important roles in differentiation, proliferation, and metastasis of many human cancers, mostly of epithelial origin." (PMID 20856931, 2010). "Overexpression and constitutive activation of EGFR in cancers are often related with a poor prognosis." (PMID 20828404, 2010). "TCPTP is a well-characterized negative regulator of several cancer relevant RTKs including EGFR, cMet, PDGFRβ, Insulin receptor, and VEGFR2." (PMID 20055993, 2010). "KRAS is a signal transducer downstream of tyrosine kinase receptors including EGFR – a complex signaling cascade involved in the development and progression of cancer." (PMID 20680106, 2010).